IL6 (interleukin 6)
Diseases named in the same sentence as IL6 in open-access papers (continued):
Sharing a sentence is not in itself a finding about the gene and the disease.
alopecia areata (7 papers, 2020 to 2025). Loss of scalp and body hair involving microscopically inflammatory patchy areas. "For instance, smoking and drinking are associated with increased production of IL-13, IFN-γ, TGF-α, and IL-6, while obesity induced by overeating may promote IL-17 production, further elevating the risk of alopecia areata." (PMID 40352276, 2025). "Conversely, IL-6 levels were higher on average in the control group at 8.315 ± 8.367 pg/mL, with a median of 3.910 pg/mL, compared to the alopecia areata group, where the average was 3.672 ± 1.016 pg/mL with a median of 3.315 pg/mL." (PMID 40352276, 2025). "Alopecia areata is also connected with changes in levels of interleukin (IL)-6, tumor necrosis factor-α, IL-1β and Type 17 cytokines." (PMID 38892934, 2024). "The efficacy of anti-IL-4 receptor alpha monoclonal antibody (dupilumab), anti-IL-13 monoclonal antibody (tralokinumab), and anti-IL-6 monoclonal antibody (siltuximab) in alopecia areata is still under investigation." (PMID 34943905, 2021). "Numerous studies showed an increased serum level of IL-6 in patients with alopecia areata compared to healthy controls." (PMID 34943905, 2021). "Expanding on this, our study examined a broader range of cytokines, including IL-2, IL-4, IL-6, IL-10, IFN-γ, and TNF-α, to evaluate their potential correlation with the onset and progression of alopecia areata in blood assays." (PMID 40352276, 2025). "Alopecia areata is characterized by systemic dysregulation of Th1 (IL-2, IFN-γ, TNF and IL-12), Th2 (IL-6), and Th17 (IL-17, IL-21) cytokines." (PMID 34943905, 2021). "The mean serum levels of IL-6, TNF-α, IL-17A, and IL-21 were comparable between the two sexes, with p values exceeding 0.05, indicating that gender did not appear to influence the systemic inflammatory response in alopecia areata." (PMID 41002719, 2025). "Although the variations in cytokines and vitamins such as IL-2, IL-4, IL-6, IL-10, TNF-α, and vitamins in the blood are insufficient to differentiate alopecia areata, we have observed a notable increase in IFN-γ and decrease in IgG4 levels among patients with this condition." (PMID 40352276, 2025). "Based on our analysis, it may be suggested that alopecia areata is characterized by the dysregulation of systemic Th1 (IL-2, IFN-γ, TNF and IL-12), Th2 (IL-6), and Th17 (IL-17, IL-21) cytokines." (PMID 34943905, 2021).
aortic atherosclerosis (7 papers, 2008 to 2023). A atherosclerosis that involves the aorta. "Our findings furnish a new mechanism through which pravastatin can prevent aortic atherosclerosis via attenuating IL-6 action by the modulation of STAT3 activity in apoE-/- mice." (PMID 19330073, 2008). "The purpose of this study was to determine whether pravastatin’s prevention of aortic atherosclerosis via attenuation of IL-6 action depends on modulation of STAT3 activity." (PMID 19330073, 2008). "Our results suggested that pravastatin’s aortic atherosclerosis preventing action via attenuation of IL-6 action may partially depend on modulation of STAT3 activity." (PMID 19330073, 2008). "Likewise, reduced total cholesterol and HDL levels, as well as increased low-density lipoprotein (LDL)/vLDL, IL-6, sRANKL and CCL5 circulating levels mirroring RA patients was observed in the K/BxAg7 mice, a novel animal model of erosive arthritis followed by prominent aortic atherosclerosis." (PMID 23941259, 2013).
aortic valve stenosis (7 papers, 2020 to 2025). Aortic valve stenosis (AVS) is a condition characterized by narrowing of the heart's aortic valve opening. "In our study, we have confirmed that polymorphisms in PALMD and IL6 genes are associated with aortic valve stenosis and the latter one, in addition, with higher circulating levels of IL-6." (PMID 36337884, 2022). "Therefore, patients carrying the CC genotype of IL6 rs1800795 polymorphism present higher levels of circulating IL-6 and this could contribute to the severity of the aortic valve stenosis." (PMID 36337884, 2022). "In this study, we investigated the influence of eLDL on IL-6 and IL-33 induction, and also the impact of eLDL on calcification in aortic valve stenosis (AS)." (PMID 37509127, 2023). "Our clinical results indicated that IL-6 and IFN-γ in the blood of children with NEC secondary intestinal stricture were raised to a certain extent during the acute phase of NEC." (PMID 35958178, 2022).
aplastic anemia (7 papers, 2012 to 2023). Anemia resulting from bone marrow failure (aplastic or hypoplastic bone marrow). "As a result, it is assumed that persistently increased IL-6 and IL-8 productivity may have the potential to cause immune-mediated bone marrow failure in aplastic anemia." (PMID 37483535, 2022). "In a mouse model of aplastic anemia induced by irradiation and spleen–thymus lymphocyte infusion, the levels of the cytokines IL-6, IL-8, IL-17, TNF-α, and IFN-γ were increased in peripheral blood and bone marrow, and an immunoinflammatory response occurred." (PMID 36976996, 2023). "The aplastic anemia patients showed significantly higher mean serum IL-6 and IL-8 levels than the controls (p<0.001)." (PMID 37483535, 2022). "In the present study, we evaluated the various haematological parameters and levels of blood IL-6 and IL-8 in aplastic anemia as well as their relationship with the severity of illness." (PMID 37483535, 2022). "Increased levels of IL-6 and IL-8 were correlated with the severity of the disease and thus seem to be crucial in aplastic anemia." (PMID 37483535, 2022). "Blood serum levels of IL-6 and IL-8 were increased in aplastic anemia and showed a correlation with the severity of the disease, hence appearing to play a vital role in aplastic anemia." (PMID 37483535, 2022). "Additional studies are required in order to further investigate the exact involvement and role of IL-6 and IL-8 in aplastic anemia." (PMID 37483535, 2022). "In this study, the level of IL-6 secreted by bone marrow stromal cells from a mouse model of aplastic anemia was analyzed." (PMID 23853724, 2013). "This study gives new insights into the hematopoiesis regulating properties of IL-6 in mice with aplastic anemia." (PMID 23853724, 2013). "IL-6 and IL-8 play a key role in the immune-mediated pathophysiology of aplastic anemia." (PMID 37483535, 2022). "Mean IL-6 and IL-8 levels were also compared according to the severity of the disease and it was observed that their levels displayed a significant incremental trend with increased severity of aplastic anemia (p<0.001)." (PMID 37483535, 2022). "Therefore, it is clear that individuals with severe and very severe cases of aplastic anemia had much higher levels of IL-6 and IL-8 in their peripheral blood than patients with the non-severe disease." (PMID 37483535, 2022). "Hence, IL-6 and IL-8 may play an important role in the immune-mediated pathophysiology of aplastic anemia and their increasing levels are giving alarming signals for timely implementation of the appropriate treatment regimen to stop further progression of the disease." (PMID 37483535, 2022). "Such advantages are repeated in severe aplastic anemia (SAA) and very severe aplastic anemia (VSAA).In conclusion, aberrant IL-6 elevations in AA patients may predict the likelihood of bacterial lung infection." (PMID 36319826, 2022). "TNF and IL6 are involved in the occurrence and development of chronic anaemia/IDA, and the level of TNF expression can reflect the degree of disease of patients with aplastic anaemia." (PMID 32345291, 2020). "Mean IL-6 and IL-8 levels in the NSAA, SAA, and VSAA groups were 26.71±33.40 and 10.29±2.63 pg/ml, 198.84±150.39 and 89.82±77.18 pg/ml, and 516.71±36.73 and 220.50±23.45 pg/ml respectively, with a significant incremental trend with increasing aplastic anemia severity (p<0.001)." (PMID 37483535, 2022).
Arthralgia (7 papers, 2018 to 2025). "Additionally, ZIKV-infected subjects with arthralgia showed higher levels of IL-1ra, whereas those with hyperemia showed lower plasma levels of IL-6, IL-7, and VEGF." (PMID 29774022, 2018). "The serological IL-2, IL-6 and INF γ levels in the presence of arthralgia elevated, while Th17 and Th17/Treg decreased." (PMID 36408259, 2022).
bone marrow fibrosis (7 papers, 2015 to 2024). "IL-6 levels are increased in primary myelofibrosis (PMF), with a positive correlation between IL-6 and angiogenesis in bone marrow of MPN patients." (PMID 26491227, 2015). "We already reported elevated plasma levels of IL-6 in patients with MPN and that IL-6 stimulated JAK2/STAT3 and AKT signaling in polycythemia vera (PV) and primary myelofibrosis (PMF)." (PMID 34206393, 2021).
C. perfringens infection (7 papers, 2020 to 2025). "C. perfringens infection increased the concentrations or activities of LPS, IL-6, CRP, PCT and MPO, causing a systemic inflammatory response to broilers, while the supplement of EA in diet relieved these adverse effects." (PMID 35436978, 2022). "In line with earlier findings in piglets and IPEC-J2 cells, we observed that C. perfringens infection significantly increased the serum levels of IL-1β, IL-6, and TNF-α, while decreasing those of IL-4 and IL-10." (PMID 40427288, 2025). "Compared to the CON group, C. perfringens infection significantly elevated serum levels of IL-1β, IL-6, and TNF-α, while suppressing IL-4 and IL-10 (p < 0.05)." (PMID 40427288, 2025). "High and Medium dose C. perfringens infection significantly increased (P < 0.05) the concentration of IL-1β, IL-6, and TNF-α compared with Control group." (PMID 35769317, 2022). "The increase in NO production and iNOS activity and increased expression of pro-inflammatory cytokines, such as IL-1β, IL-6, iNOS, and IFN-γ demonstrate that C. perfringens infection induces a strong inflammatory response and causes severe tissue damage." (PMID 33679724, 2020). "Unlike LPS, there was a lower production of TNF-α and IL-6 response to C. perfringens infection under HKCA training compared with the control group." (PMID 38622656, 2024). "Although HKCA-trained PM produced decreased levels of TNF-α and IL-6, the importance of trained immunity was demonstrated by the fact that HKCA training resulted in enhanced bacterial phagocytic ability and clearance in vivo and in vitro during C. perfringens infection." (PMID 38622656, 2024).
Cholecystitis (7 papers, 2016 to 2025). The presence of inflammatory changes in the gallbladder. "Our findings indicate that resveratrol pharmacologically activates PPAR-γ, downregulates the expression of inflammatory cytokine proteins such as NF-κB and IL-6, and alleviates liver and gallbladder inflammation." (PMID 40166468, 2025). "Among all the changed miRNAs in miRNA profiling, miR-33a expression was significantly decreased in IL-6 treated GBC cell lines, as well as in GBC tissues compared with case-matched normal tissues and cholecystitis tissues." (PMID 27769047, 2016). "In case of severe inflammatory response, both IL-6 and TNF-α activate the coagulation cascade, explaining the presence of thrombosed vessels in the gallbladder and the occurrence of an ischemic gangrenous cholecystitis." (PMID 32615987, 2020). "While the precise correlation between cholecystitis and GBC remains unclear, a proposed mechanism involves recurrent acute cholecystitis, leading to the release of pro-inflammatory cytokines such as IL-1, IL-6, and tumour necrosis factor-alpha (TNF-α)." (PMID 40142228, 2025).
chondrosarcoma (7 papers, 2010 to 2024). A malignant cartilaginous matrix-producing mesenchymal neoplasm arising from the bone and soft tissue. "This growth inhibitory effect is also observed with two other cytokines of the same family able to reduce chondrosarcoma expansion but with a lower efficiency: IL-6 in association with its soluble receptor and IL-27." (PMID 21647363, 2011). "In SW1353 chondrosarcoma cells, IL-1β (interleukin-1β) induces overexpression of IL-6 (interleukin-6), PGE2 (prostaglandin E2) and Cox-2 (cyclooxygenase 2), which, in turn, activate a series of MMPs, such as MMP-1 and MMP-13." (PMID 31546898, 2019). "Oncostatin M, a member of the IL-6 cytokine family mainly produced by macrophages, neutrophils, and T lymphocytes, is a cytostatic factor for chondrosarcomas in vitro and in vivo." (PMID 21647363, 2011). "Here, we show that other genes under NF-κB control, such as IL-6, IL-8, ICAM-1 and Mcp-1, are modulated as well in the HTB-94 chondrosarcoma cell line stimulated with TNFα." (PMID 20113495, 2010). "Meanwhile, in OUMS-27 cells (a human chondrosarcoma cell line), both TNF-α, IL-1β, and IL-6 could upregulate KIAA1199 expression." (PMID 37569797, 2023).
conjunctivitis (7 papers, 2019 to 2025). Inflammation of the conjunctiva of the eye. "Here, the NLRP3 inflammasome is a major driver in releasing pro-inflammatory factors such as IL-6 and caspase-1, leading to follicular conjunctivitis and bulbar congestion, even as isolated signs in the ‘asymptomatic’ patient." (PMID 37764042, 2023).
Dengue hemorrhagic fever (7 papers, 2017 to 2024). A serious condition caused by Dengue virus infection. "In patients with Dengue hemorrhagic fever and hyperinflammation, doxycycline substantially reduces mortality in association with a significant reduction in serum concentrations of interleukin-6, TNFα and interleukin-1." (PMID 36689456, 2023). "THP-1 cells infected with dengue virus induced elevated levels of dengue hemorrhagic fever (DHF)-associated immunomediators such as interleukin (IL)-6, IL-8, interferon γ-induced protein-10 (IP-10), tumor necrosis factor alpha (TNFα) or IFNγ." (PMID 28788062, 2017). "Patients who experienced severe COVID-19 pneumonia and dengue hemorrhagic fever (DHF) had notably higher levels of IL-6, IL-10, and MIP3α during disease onset compared to those with mild disease." (PMID 39519178, 2024).
developmental delay (7 papers, 2017 to 2025). "IL-6 is known to be involved in MIA-mediated neurodevelopmental changes in mice and elevated maternal IL-6 during pregnancy is associated with increased risk of developmental delay in humans." (PMID 37514044, 2023). "There was a direct correlation (96%) between IL-6 level and the severity of the developmental delay." (PMID 34282369, 2021). "On one hand, the findings of the present study revealed a direct correlation between IL-6 concentration and the severity of developmental delay, which supports its destructive role." (PMID 34282369, 2021). "In earlier studies, the combination of serum levels of IL-6 (>41 pg/ml) along with moderate to severe HIE has been suggested as a prognostic biomarker for diagnosis of developmental delay and even early death." (PMID 34282369, 2021). "For neonates with an IL-6 level of >25, 62, and 101pg/ml, the child has mild, moderate, and severe developmental delays at the age of 2 years, respectively." (PMID 34282369, 2021). "The release of IL‐6 triggers an inflammatory cascade secondary to infection, with consequent developmental delay and/or brain injury." (PMID 28553016, 2017). "The Early markers for Autism study found that high levels of IL-4, IL-5 and interferon-γ (IFN-γ) in maternal serum at 15–19 weeks of gestation were associated with a 50% higher risk of ASD, whereas high levels of IL-2, IL-4 and IL-6 was associated with developmental delay in the absence of ASD." (PMID 35222122, 2022). "When followed for two years, neonatal IL-6 concentrations above 24 nl/L combined with HIE grades of 2 and 3 and acidosis indicated a high mortality rate and developmental delay among survivors." (PMID 34282369, 2021). "There was a statistically significant difference concerning the mean IL-6 concentrations between the control group with the normal outcome (no developmental delay) and those with different levels of developmental delay." (PMID 34282369, 2021). "While, initially, the IL-6 level was 4 (No developmental delay), it increased up to 50, 173, and 225 ng/ml in those with mild, moderate, and severe developmental delay, respectively." (PMID 34282369, 2021). "Using a larger sample set, a subsequent analysis found high levels of many cytokines, including IL-1α and IL-6, in mothers of children with ASD and developmental delay compared with children with ASD without developmental delay and controls." (PMID 35222122, 2022). "Regardless of the first hour IL-6 concentration, 83% of the neonates with HIE grade of 3 would die within two years and all survivors will probably develop severe developmental delay." (PMID 34282369, 2021).
Dysmenorrhea (7 papers, 2020 to 2025). Pain during menstruation that interferes with daily activities. "Excluding participants with extrapolated biomarker levels, we observed similar associations between dysmenorrhea severity and IL-6." (PMID 40508188, 2025). "Also, oxidative stress and increased serum levels of the cytokines malondialdehyde and interleukin-6 are associated with dysmenorrhea." (PMID 34222182, 2021). "Currently, studies have proved that it is an effective way to treat dysmenorrhea by regulating IL-6 concentration." (PMID 35069759, 2022). "Increased IL6 concentration in women with dysmenorrhea has also been shown in other studies." (PMID 32069859, 2020). "Plasma IL6 and TNFα levels were found to be higher in women with dysmenorrhea compared to women without menstrual disorders." (PMID 32069859, 2020).
endocarditis (7 papers, 2017 to 2024). Inflammation of the endocardium. "Elevated levels of IL-6 have been linked to the severity of endocarditis." (PMID 37510130, 2023). "Therefore, although elevated IL-6 levels may indicate the presence of endocarditis, additional diagnostic testing is required for a definitive diagnosis." (PMID 37510130, 2023). "Another study in patients with endocarditis showed postoperative IL-6 and IL-8 reduction and comparable hemodynamic stability in 39 patients treated with HA." (PMID 33546164, 2021). "S. mutans Gtfs furthermore robustly induce the production of IL-6 by T-cells in vitro as well as in vivo in a experimental rat model of endocarditis – pinpointing their contribution to disease development outside the oral cavity, since IL-6 levels were found to be elevated in patients with IE." (PMID 38456080, 2024). "However, it is crucial to acknowledge that IL-6 is a non-specific marker of inflammation and may not be exclusive to endocarditis." (PMID 37510130, 2023). "In contrast to Dufour’s conclusions that phage therapy did not induce an inflammatory response, phage therapy for endocarditis in rats induced by P. aeruginosa showed that phage therapy, but not ciprofloxacin, correlated with significantly increased plasma levels of IL-1β and IL-6." (PMID 34209836, 2021).
enteropathy (7 papers, 2014 to 2025). "The observed mucosal barrier changes were similar to previous reports on AOM/DSS-induced enteropathy, mainly featured by losing the expression of ZO-1 and occluding and blooming release of inflammatory factors, IL-1β and -IL6." (PMID 37200915, 2023). "The lack of occupancy of this and other pathways crucial to the pathogenesis of NSAID enteropathy in the colonic data, including apoptosis, and IL-1 and IL-6 pathways, provide further evidence that the exfoliome signature reflects the SI mucosa in the presence of SI disease." (PMID 29089621, 2017). "In the present study, there was a strong correlation (ρ = 0.70) between IL-6 and MMP-1, suggesting that this could be one mechanism through which NTMs could lead to tissue re-modelling in enteropathy." (PMID 29680481, 2018).